GNB4 (G protein subunit beta 4)
Diseases named in the same sentence as GNB4 in open-access papers:
GNB4 is named in the same sentence as 26 diseases in open-access papers, as found by Europe PMC text mining. Sharing a sentence is not in itself a finding about the gene and the disease. The quoted sentences say what the papers report.
breast carcinoma (9 papers, 2018 to 2025). "Study has showed that GNB4 promotes the tumor progression and chemoresistance in breast cancer, and the high expression of this gene is associated with worse survival rate of colorectal cancer." (PMID 35111198, 2021). "GNB4 has been reported to be related to the prognosis in patients with urothelial bladder and colorectal carcinomas and shown to be involved in breast cancer cell growth." (PMID 40948637, 2025). "The haplotype block in intron 1 of GNB4 is significantly related to bladder urothelial carcinoma development and prognosis; the high GNB4 expression is in a significant correlation with the survival rate in patients having breast cancer or colorectal cancer." (PMID 35756485, 2022). "DNMT3B targets GNB4 DNA methylation in breast cancer cells, contributing to downregulation of DNA methylation and suppression of proliferation of breast cancer cells." (PMID 35620052, 2022). "Our results suggest that GNB4 is a drug-resistant gene in fulvestrant- and tamoxifen-resistant breast cancer cells." (PMID 30103729, 2018). "We next looked at the potential role of GNB4 in controlling the cell cycle and apoptosis of antiestrogen-resistant breast cancer cells." (PMID 30103729, 2018). "GNB4 has been reported to be downregulated in progressive breast cancer due to the acquired tamoxifen resistance, which is consistent with our results." (PMID 30103729, 2018). "Our results provide novel insight into the role of GNB4 in the growth of both antiestrogen-resistant and sensitive breast cancer cells and may represent a target for treatment of breast cancer." (PMID 30103729, 2018). "We showed here that GNB4 was downregulated in both fulvestrant- and tamoxifen-resistant breast cancer cell lines, and that this was attributed to DNMT3B-mediated DNA methylation, because knockdown of DNMT3B by siRNA significantly elevated the expression of GNB4 at both mRNA and protein levels." (PMID 30103729, 2018). "Furthermore, knockdown of GNB4 decreased growth of both antiestrogen resistant and sensitive breast cancer cells." (PMID 30103729, 2018). "Since GNB4 was downregulated in antiestrogen-resistant breast cancer cells, we hypothesized that GNB4 may function as an “antidrug-resistant” gene that may restore the sensitivity of resistant cell lines to either fulvestrant or tamoxifen." (PMID 30103729, 2018). "To test our hypothesis by determining the role of GNB4 in the development of acquired fulvestrant and tamoxifen resistance in breast cancer, we generated GNB4 stable-expressing 182R-6 and TAMR-1 cell lines." (PMID 30103729, 2018). "Importantly, we found that the ectopic expression of GNB4 remarkably promoted the proliferation of antiestrogen-resistant breast cancer cells in response to antiestrogen drugs." (PMID 30103729, 2018). "GNB4 is important for growth of breast cancer cells and a potential target for treatment." (PMID 30103729, 2018). "It has been reported that GNB4 was identified as a potential target silenced by DNA methylation via DNA methyltransferase 3B (DNMT3B), which can promote the growth of breast cancer cells." (PMID 36479252, 2022). "Network analysis on the cancer genome atlas (TCGA) breast cancer dataset revealed interaction between CXCL12 and CXCR7 (ACKR3), and a number of G-protein family members (GNG5, GNB4, GNB2, GNG12, GNG7, GNGT1, and GNAI3)." (PMID 30993013, 2019). "Moreover, knockdown of GNB4 also inhibited proliferation of the parental S05 cells in the absence of antiestrogen drugs, in addition to a role in drug resistance, may also implicating a role in the development of breast cancer." (PMID 30103729, 2018). "In this study, we globally analyzed genomic DNA methylation, correlated with gene expression profiling, and identified GNB4 that was silenced by DNMT3B-mediated DNA methylation in both fulvestrant-resistant (MCF-7/182R-6) and tamoxifen-resistant (MCF-7/TAMR-1) breast cancer cell lines." (PMID 30103729, 2018).
gastric cancer (6 papers, 2022 to 2025). A primary or metastatic malignant neoplasm involving the stomach. "In conclusion, GNB4 is a gene which shows association with the immune microenvironment of gastric cancer." (PMID 35756485, 2022). "One such gene was GNB4, which prior studies have identified as associated with gastric cancer." (PMID 38920660, 2024). "Based on the obtained results, immunity and metabolism might also become the underlying mechanism for involving GNB4 in both the incidence and progress of gastric cancer." (PMID 35756485, 2022). "High expression of guanine nucleotide-binding protein subunit beta-4 (GNB4) in gastric cancer (GC) patients is significantly associated with poor survival prognosis." (PMID 40654572, 2025). "TET1 binds to the guanine nucleotide‐binding protein subunit beta‐4 (GNB4) promoter region, which promotes gastric cancer proliferation and metastasis by activating the transcription of GNB4 and activation of the Hippo‐Yes‐associated protein 1 pathway." (PMID 40599235, 2025). "At last, we adopted TISDIB and TIMER databases for analyzing the association of guanine nucleotide binding protein subunit-4 (GNB4) between gastric cancer and tumor immune cells." (PMID 35756485, 2022). "qRT-PCR demonstrated that GNB4 expression in gastric cancer was notably higher in comparison with that in normal gastric mucosa, showing significant association with matrix TILs." (PMID 35756485, 2022). "One central gene, namely, guanine nucleotide binding protein subunit-4 (GNB4), was verified as a prognosis-related biomarker of gastric cancer and further analysed." (PMID 35756485, 2022). "Although high GNB4 expression of gastric cancer tissues was confirmed through qRT-PCR, in vivo and in vitro research and more prospective clinical trials should be performed to verify GNB4's role in gastric cancer." (PMID 35756485, 2022). "TISDIB and TIMER databases were used to comprehensively study the state of GNB4 in gastric cancer-infiltrating immune cells in gastric cancer microenvironment." (PMID 35756485, 2022). "This study applied the TIMER database for studying connection of GNB4 expression with infiltrating immune cells within gastric cancer." (PMID 35756485, 2022). "Oncomine and GEPIA database analysis revealed that gastric cancer tissues had higher GNB4 expression compared with normal gastric mucosa (P < 0.01 and P = 0.019, respectively)." (PMID 35756485, 2022). "Oncomine and GEPIA databases revealed that GNB4 expression in gastric cancer was obviously higher in comparison with that in normal gastric mucosa." (PMID 35756485, 2022). "We further studied the underlying mechanism for GNB4 in gastric cancer by GSEA, observing the potential involvement of high GNB4 expression in tumor-related signalling pathways and immune and metabolic processes." (PMID 35756485, 2022). "Obviously, in gastric cancer, GNB4 possibly acts as a biomarker for abnormal methylation, playing a vital function in the growth and metastasis of Helicobacter pylori-induced gastric cancer." (PMID 35756485, 2022). "In conclusion, the hub gene GNB4 can be further studied as a molecular marker for clinically treating and preventing gastric cancer." (PMID 35756485, 2022). "GNB4 mRNA level was compared with the normal tissues adjacent to cancer cells in patients undergoing gastric cancer." (PMID 35756485, 2022). "The qRT-PCR results of the research indicate the remarkably elevated GNB4 expression of gastric cancer tissues (P = 0.003), in agreement with former studies." (PMID 35756485, 2022). "In addition to GNB4, certain genes play a role in promoting the development of precursor lesions to gastric cancer." (PMID 40654572, 2025). "In addition, it can be observed that GNB4 is not only related to gastric cancer but also significantly related to the adverse prognosis of leukemia, bladder cancer, glioma, etc.." (PMID 35756485, 2022). "The selected key gene GNB4 is a potential biomarker to guide the immunotherapy of gastric cancer." (PMID 35756485, 2022).
gastric cancer (continued). "To conclude, the results indicated that GNB4 may become a different prognostic biomarker and therapeutic target in gastric cancer immunotherapy." (PMID 35756485, 2022). "As suggested by enrichment analysis, immune-cell-related pathway and cytokine–cytokine receptor interaction are involved notably; this study investigated whether immune cell GNB4 infiltration is engaged in gastric cancer (GC) pathogenesis." (PMID 35756485, 2022). "Therefore, we investigated whether methylation modification is the central mechanism triggering GNB4-induced proliferation and metastasis of gastric cancer cells." (PMID 37016382, 2023). "Though GNB4's clinical importance and function in gastric cancer have been reported, the research verified the potential use of GNB4 as a prognostic biomarker and provided some ideas for studying the potential mechanism of GNB4 involved in tumor immune cell infiltration." (PMID 35756485, 2022). "Furthermore, GNB4 expression was in a significant correlation with gastric cancer patients' pathological stage and tumor invasion depth, as well as survival rate; in vitro tests verify the positive effect of GNB4 overexpression during epithelial−mesenchymal transformation (EMT)." (PMID 35756485, 2022).
Charcot-Marie-Tooth disease (3 papers, 2018 to 2022). "A study identified GNB4 mutations as a cause of Charcot-Marie-Tooth disease (CMT) and emphasized the importance of Gβ4-related GPCR signals for human peripheral nerve function." (PMID 35841000, 2022). "For the variants of GNB4 an association with Charcot-Marie-Tooth disease and refractive disorders was described." (PMID 36077181, 2022). "GNB4 may be one of the key genes that cause Charcot-Marie-Tooth disease, a heterogeneous group of the inherited neuropathies." (PMID 30103729, 2018).
bladder urothelial carcinoma (2 papers, 2018 to 2022). "Haplotypes of GNB4 intron-1 have been shown to be associated with the survival rate of patients with colorectal and urothelial bladder carcinomas." (PMID 30103729, 2018).
neuropathies (2 papers, 2018 to 2021). "Therefore, we suggest that the examined GNB4 mutations had phenotypic heterogeneity including intermediate neuropathy and demyelinating neuropathy." (PMID 34071515, 2021). "Therefore, it seems that the investigated GNB4 mutations do cause not only the known intermediate type but also demyelinating-type neuropathy." (PMID 34071515, 2021). "Moreover, the GNB4 mutation has been described as causing CMTDIF since it was reported as a dominant intermediate neuropathy." (PMID 34071515, 2021). "Therefore, the GNB4 mutations cause not only the known intermediate neuropathy but also demyelinating neuropathy." (PMID 34071515, 2021).
atrial fibrillation (1 paper, 2025). A disorder characterized by an electrocardiographic finding of a supraventricular arrhythmia characterized by the replacement of consistent P waves by rapid oscillations or fibrillatory waves that vary in size, shape and timing and are accompanied by an irregular ventricular response. "GNB4 is associated with atrial fibrillation and resting heart rate and is involved in cardiac electrophysiological regulation." (PMID 41301959, 2025).
cardiomyopathy (1 paper, 2021). A disease of the heart muscle or myocardium proper. "The upregulated hub genes ADCY2, CXCL12, and GNB4 were enriched in calcium signal pathway, dilated cardiomyopathy, hypertrophic cardiomyopathy, neuroactive ligand-receptor interaction pathway, and vascular smooth muscle contraction pathways related to cardiomyopathy." (PMID 34603374, 2021).
colon cancers (1 paper, 2020). "GNB4, a signal transduction molecule involved in the PI3K-AKT pathway, is hypermethylated and down-regulated in both CRC cell lines and colon cancers." (PMID 33258470, 2020).
inflammatory bowel disease (1 paper, 2021). A spectrum of small and large bowel inflammatory diseases of unknown etiology. "Previous study found that GNB4 can be a candidate diagnostic biomarker in inflammatory bowel diseases." (PMID 34271942, 2021).
lymph node metastasis (1 paper, 2023). "Furthermore, receiver operator characteristic (ROC) curves indicated that GNB4 expression could be applied to distinguish patients with GC with or without lymph node metastasis with an area under the ROC curve (AUC) of 0.576 (P < 0.05)." (PMID 37016382, 2023).
myopia (1 paper, 2008). "GNB4 is of interest as a myopia susceptibility gene, as the Gβ4 protein has been shown to be expressed in retinal ON bipolar cells." (PMID 18846214, 2008).
Parkinson disease (1 paper, 2023). A progressive degenerative disorder of the central nervous system characterized by loss of dopamine producing neurons in the substantia nigra and the presence of Lewy bodies in the substantia nigra and locus coeruleus. "The CREB5/CACNA1B/GNB4/PPP2R5A gene was found to be closely related to Parkinson’s disease in pathways of dopaminergic synapses." (PMID 37323142, 2023).
cancer (13 papers, 2018 to 2025). A tumor composed of atypical neoplastic, often pleomorphic cells that invade other tissues. "GNB4 enriches 72 gene sets, including 12 gene sets associated with cancer-related processes." (PMID 35756485, 2022). "CHST2, SPACA6, and TSC22D1 had lower methylation levels in cancer tissues than Riplet and GNB4, in which CHST2 and TSC22D1 had higher methylation levels in normal tissues." (PMID 38154055, 2024). "In addition, guanine nucleotide-binding protein subunit beta-4 plays a crucial role in the initiation and progression of cancers, including GC." (PMID 39273456, 2024). "In addition, functional experiments demonstrated that the cancer-promoting function of GNB4 was inhibited after the YAP1–TEADs interaction was disrupted by VP addition." (PMID 37016382, 2023). "Additionally, inhibition of YAP1 expression significantly blocked the pro-cancer function of GNB4 in H. pylori-induced GC models." (PMID 37016382, 2023). "Therefore, the role of this pathway in the pro-cancer function of GNB4 should be further investigated." (PMID 37016382, 2023). "Interestingly, GNB4, a gene encoding a beta subunit in the heterotrimeric G proteins that, plays a crucial role in the GPCR-mediated signaling transduction, has been linked to cancer." (PMID 40948637, 2025). "Taken together, GNB4 may have a cancer-promoting function through the Hippo–YAP1 pathway." (PMID 37016382, 2023). "Given that the levels of GNB4 correlated with EMT and H. pylori infection, we investigated whether H. pylori could exert its cancer-promoting effects through GNB4." (PMID 37016382, 2023).
tumor (9 papers, 2018 to 2026). "Spearman's correlation demonstrated association of the tumor GNB4 mRNA level with TILs (r = 0.528, P = 0.002)." (PMID 35756485, 2022). "Notably, genes implicated in oncogenic signaling and tumor progression, including GNB4, EGF, MYB, IL6R, ANGPT4, and ITGB8, were consistently downregulated in both BxPC3 and SW1990 cells following PCDH1 silencing." (PMID 41602375, 2026). "GNB4 expression was notably related to the tumor-associated macrophage (TAM) markers CCL2 (Cor = 0.527, P = 1.64e−28), IL10 (Cor = 0.61, P = 5.02e−40), M2 macrophage marker CD163 (Cor = 0.66, P = 1.01e−48), VSIG4 (Cor = 0.64, P = 5.17e−45), and MS4A4A (Cor = 0.723, P = 1.26e−62)." (PMID 35756485, 2022). "The results showed that the methylation levels of GNB4 and Riplet showed a gradual increase corresponding to larger tumour size and greater tumour number." (PMID 38154055, 2024). "We found that GNB4 overexpression promoted tumor growth and increased tumor weight, but treatment with VP inhibited this effect (P < 0.01)." (PMID 37016382, 2023). "The GSEA, TISDIB, and TIMER databases revealed that GNB4 is involved in various tumor signal pathways and immune and metabolic processes." (PMID 35756485, 2022). "According to bioinformatic analysis, GNB4 is involved in tumor-related signalling pathways and immune and metabolic processes." (PMID 35756485, 2022). "qRT-PCR was applied for exploring differential GNB4 expression between GC and normal gastric mucosa and investigating the relation of GNB4 with tumor-infiltrating lymphocytes (TILs)." (PMID 35756485, 2022). "Few studies have investigated the DNA methylation modulation of GNB4 in tumor tissues." (PMID 37016382, 2023). "Moreover, analysis of stomach tissues in the public data set of Prom1-conditional mutant mouse GC model from the GEO database (GSE40634) demonstrated significant overexpression of GNB4 mRNA in the mouse tumor tissues (P < 0.0001)." (PMID 37016382, 2023). "In comparison, the expression of GNB4 and NSF in tumor tissues was significantly lower than that in normal tissues, suggesting that these key genes play an essential role in the occurrence and development of ccRCC." (PMID 36237326, 2022). "Furthermore, the IHC analysis of human GC tissues from our cohort showed high levels of GNB4 protein in H. pylori-positive (HP+) tumor tissue samples compared to those in H. pylori-negative (HP−) samples (P < 0.05)." (PMID 37016382, 2023).
infection (1 paper, 2023). The state of being infected such as from the introduction of a foreign agent such as serum, vaccine, antigenic substance or organism. "Then, qRT-PCR results showed that GNB4 mRNA expression was significantly induced in GC cell lines after 6 h of infection with H. pylori strains (P < 0.001)." (PMID 37016382, 2023). "Western blot analysis showed that H. pylori infection significantly upregulated GNB4 protein levels in the human GC cell lines, and the upregulation was highest at 6 h post-infection." (PMID 37016382, 2023). "Therefore, we aimed to evaluate the demethylated modulation of GNB4 by TETs in H. pylori-infected infection models." (PMID 37016382, 2023). "Furthermore, wound healing and transwell assays showed that the migration and invasive abilities of MKN45 and AGS cells were enhanced after infection with H. pylori strain (26695 or SS1) infection; however, GNB4 knockdown diminished these abilities (P < 0.001)." (PMID 37016382, 2023). "Infection with H. pylori strains 26695 and SS1 induced GNB4 mRNA and protein expression in GC cell lines and mice." (PMID 37016382, 2023).
GNB4 also shares sentences with these, for which no sentence is quoted: colorectal cancer (3 papers); glioma (2); bladder cancer (1); cervical cancer (1); dilated cardiomyopathy (1); Gaucher disease (1); hepatocellular carcinoma (1); hypertrophic cardiomyopathy (1); leukemia (1); melanoma (1); triple-negative breast carcinoma (1).